CHODL (chondrolectin)
Description:
May play a role in the development of the nervous system such as in neurite outgrowth and elongation. May be involved in motor axon growth and guidance.
Synonyms: C21orf68; PRED12; FLJ12627; MT75
Tractability: Antibody: UniProt predicts a signal peptide or a membrane-spanning region.
Gene: Protein-coding gene on chromosome 21 (17,901,263 to 18,267,373, forward strand). Ensembl gene ENSG00000154645.
Subcellular location: Cytoplasm; Membrane; Endoplasmic reticulum (Isoform 2); Endoplasmic reticulum membrane; Cytoplasm (Isoform 3)
Subcellular location (Human Protein Atlas): Cytosol; Centrosome
Gene Ontology:
Molecular function: hyaluronic acid binding; protein binding
Biological process: muscle organ development; positive regulation of axonogenesis
Cellular component: cytoplasm; endoplasmic reticulum; perinuclear region of cytoplasm; endoplasmic reticulum membrane; membrane
Genetic constraint (gnomAD): Loss-of-function variants: 23 observed, 25.05 expected, observed/expected ratio (o/e) 0.92, 90% interval 0.66 to 1.3. The upper end of that interval is the gene's LOEUF score, 1.3, which puts it in group 5 of 6, group 1 being the genes least tolerant of losing a copy. Missense variants: 248 observed, 252.71 expected, observed/expected ratio (o/e) 0.98, 90% interval 0.88 to 1.09. Synonymous variants: 94 observed, 84.66 expected, observed/expected ratio (o/e) 1.11, 90% interval 0.94 to 1.32.
Homologues: Orthologues: macaque CHODL (99% identical), pig CHODL (95% identical), dog CHODL (95% identical), rat Chodl (94% identical), mouse Chodl (85% identical), guinea pig CHODL (85% identical), chimpanzee CHODL (80% identical), tropical clawed frog chodl (65% identical), zebrafish chodl (58% identical). Paralogues in human: LAYN (50% identical).
Diseases named in the same sentence as CHODL in open-access papers:
CHODL is named in the same sentence as 9 diseases in open-access papers, as found by Europe PMC text mining. Sharing a sentence is not in itself a finding about the gene and the disease. The quoted sentences say what the papers report.
breast carcinoma (2 papers, 2020 to 2022). "Novel 5-hmC candidates such as TXNL1, CNIH3, BNIPL, and CHODL were found to be promising diagnostic and therapeutic markers for breast cancer." (PMID 36230901, 2022). "Our validation analysis confirmed that the gain of 5-hmC in TXNL1, BNIPL, CNIH3 and loss of 5-hmC in CHODL, ZBTB16, SP8, and HIC2 in breast cancer samples." (PMID 36230901, 2022).
lung carcinoma (2 papers, 2020 to 2024). "Moreover, the expression of CHODL, screened through a comprehensive analysis of gene transactivation in lung cancers, has been correlated with the clinicopathologic significance in patient tissues." (PMID 38975339, 2024).
hepatocellular carcinoma (1 paper, 2020). A malignant tumor that arises from hepatocytes. "Other researches showed that overexpression of human CHODL was associated with the metastasis of hepatocellular carcinoma and was also showed that CHODL could be an independent prognostic factor in HCC based on TCGA and GEO database." (PMID 32226505, 2020).
rectal cancer (1 paper, 2020). A primary or metastatic malignant neoplasm that affects the rectum. "Analysis of the clinical data for IHC samples showed that high CHODL expression in rectal cancer samples (p<0.05), but not all CRC samples, was associated with a significantly improved prognosis." (PMID 32226505, 2020).
spinal muscular atrophy (1 paper, 2020). A motor neuron disease that affect the muscles, and characterized by muscle weakness and atrophy resulting from progressive degeneration and irreversible loss of the anterior horn cells in the spinal cord (i.e., lower motor neurons) and the brain stem nuclei. "In the motor neuron degenerative disease spinal muscular atrophy model, CHODL was found to have mRNA splicing disorder which can affect motor neuron mature." (PMID 32226505, 2020). "Aberrant CHODL expression was found in spinal muscular atrophy mouse models." (PMID 32226505, 2020).
tumor (4 papers, 2020 to 2024). "In the univariate Cox regression analysis, tumor stage and patient age were significant prognostic factors (p<0.0001), and the methylation level of CHODL was also associated with an increased risk of cancer-related death (relative risk [RR], 0.467; 95% confidence interval [CI], 0.269-0.809; p<0.05)." (PMID 32226505, 2020). "Our findings suggest that CHODL is a metastasis-related gene that promotes HGSOC cell migration and invasion, and its high expression in the tumor tissues is associated with poor prognosis." (PMID 38975339, 2024). "Given the higher risk coefficient of CHODL, we examined the tumor tissues from HGSOC patients, and found that the expression of CHODL was higher in the metastasis tissues compared to that of primary tissues." (PMID 38975339, 2024). "Further verification using TCGA data showed that promoter hypermethylation of CHODL was the predominant mechanism for the silencing of the CHODL gene in CRC and that CHODL had a tumor-suppressive role in CRC." (PMID 32226505, 2020). "Our results from the in vivo model provide additional support for the tumor-suppressive role of CHODL in CRC." (PMID 32226505, 2020). "Based on the tumor-suppressive role of CHODL identified both in vitro and in vivo, we further investigated the clinical value of CHODL as a predictor of CRC prognosis." (PMID 32226505, 2020). "In this study, we showed that CHODL was silenced in CRC cell lines and tumor tissues and frequently expressed in normal colonic tissues." (PMID 32226505, 2020). "The silencing of CHODL in CRC cell lines and tissues suggests that CHODL has a tumor-suppressive function in CRC tumorigenesis." (PMID 32226505, 2020). "The results showed that CHODL was significantly downregulated in 92% (22/24) of the CRC tumor tissues compared with its expression in the adjacent nontumor tissues (p<0.0001)." (PMID 32226505, 2020). "Collectively, the findings of this research are consistent with the hypothesis that the aberrant epigenetic inactivation of CHODL contributes to CRC tumorigenesis and that CHODL acts as a tumor suppressor in CRC development." (PMID 32226505, 2020). "First, we examined the mRNA expression of CHODL using real-time PCR in 24 paired CRC tumor tissues and their adjacent nontumor samples." (PMID 32226505, 2020).
cancer (2 papers, 2020 to 2024). A tumor composed of atypical neoplastic, often pleomorphic cells that invade other tissues. "We also found that these cells express unique markers like PAX7 (paired box 7) and CHODL (chondrolectin), which can potentially be used to identify these cells in human cancers." (PMID 38273014, 2024). "Through functional assays and RNA-Seq, we identified a relationship between low CHODL expression and malignant cancer phenotypes, but the mechanism by which CHODL suppresses malignancy in CRC is still unclear." (PMID 32226505, 2020). "Collectively, these data indicate that the effects of CHODL inactivation on specific cellular pathways are important in cancer development." (PMID 32226505, 2020).
CHODL also shares sentences with these, for which no sentence is quoted: Alzheimer disease (1 paper); colorectal tumors (1).